FLI1 (Fli-1 proto-oncogene, ETS transcription factor)
Description:
Sequence-specific transcriptional activator. Recognizes the DNA sequence 5'-C[CA]GGAAGT-3'.
Synonyms: SIC-1; EWSR2; FLI-1; BDPLT21
Tractability: Small molecule: a high-quality ligand is known. PROTAC: ubiquitination databases record sites on it; its protein half-life has been measured; a small molecule that binds it is known.
Target class: Transcription factor
Gene: Protein-coding gene on chromosome 11 (128,686,535 to 128,813,267, forward strand). Ensembl gene ENSG00000151702.
Subcellular location: Nucleus
Subcellular location (Human Protein Atlas): Nuclear bodies; Nucleoplasm
Pathways (Reactome):
Developmental Biology: Transcriptional regulation of granulopoiesis
Gene Ontology:
Molecular function: protein binding; sequence-specific double-stranded DNA binding; transcription cis-regulatory region binding; DNA binding; DNA-binding transcription factor activity; DNA-binding transcription factor activity, RNA polymerase II-specific; chromatin binding; DNA-binding transcription activator activity, RNA polymerase II-specific; RNA polymerase II cis-regulatory region sequence-specific DNA binding; sequence-specific DNA binding
Biological process: positive regulation of DNA-templated transcription; animal organ morphogenesis; cell differentiation; hemostasis; regulation of transcription by RNA polymerase II; positive regulation of transcription by RNA polymerase II; regulation of DNA-templated transcription
Cellular component: nuclear body; nucleoplasm; nucleus; chromatin
Genetic constraint (gnomAD): Loss-of-function variants: 10 observed, 46.26 expected, observed/expected ratio (o/e) 0.22, 90% interval 0.13 to 0.37. The upper end of that interval is the gene's LOEUF score, 0.37, which puts it in group 1 of 6, group 1 being the genes least tolerant of losing a copy. Missense variants: 376 observed, 569.5 expected, observed/expected ratio (o/e) 0.66, 90% interval 0.61 to 0.72. Synonymous variants: 227 observed, 226.79 expected, observed/expected ratio (o/e) 1, 90% interval 0.9 to 1.12.
Gene-disease validity (ClinGen):
ClinGen rates the evidence that FLI1 causes each of these diseases.
bleeding disorder, platelet-type, 21 (autosomal dominant): Moderate.
Homologues: Orthologues: chimpanzee FLI1 (100% identical), macaque FLI1 (98% identical), guinea pig FLI1 (97% identical), mouse Fli1 (97% identical), dog FLI1 (96% identical), rat Fli1 (96% identical), pig FLI1 (95% identical), rabbit FLI1 (95% identical), tropical clawed frog fli1 (82% identical), zebrafish fli1 (80% identical). Paralogues in human: ERG (67% identical), ETS1 (28% identical), GABPA (27% identical), ETS2 (26% identical), FEV (25% identical), ETV1 (21% identical), ETV2 (20% identical), ETV5 (19% identical), ETV6 (19% identical), ETV4 (19% identical), SPDEF (18% identical), ELK4 (18% identical), and 16 more.
Diseases named in the same sentence as FLI1 in open-access papers:
FLI1 is named in the same sentence as 251 diseases in open-access papers, as found by Europe PMC text mining. Sharing a sentence is not in itself a finding about the gene and the disease. The quoted sentences say what the papers report.
Ewing sarcoma (599 papers, 1994 to 2026). A small round cell tumor that lacks morphologic, immunohistochemical, and electron microscopic evidence of neuroectodermal differentiation. "We have tested examples of Ewing sarcoma cell lines expressing EWS-FLI1, a fusion of the EWSR1 and FLI1 proteins, which is the driving mutation for 85% of Ewing sarcoma tumors." (PMID 40909543, 2025). "Tumor transcriptome analysis identified an EWSR1::FLI1 fusion, with breakpoints distinct from those typically associated with Ewing's sarcoma." (PMID 40630716, 2025). "FLI-1 is also implicated in pathological processes, as its dysregulation contributes to the development of various malignancies, including Ewing’s sarcoma, erythroleukemia, B-cell lymphomas, and AS." (PMID 40666093, 2025). "An EWSR1::FLI1 fusion was detected, a hallmark cytogenetic abnormality in Ewing sarcoma (EWS), seen in 85% of cases." (PMID 40630716, 2025). "Examples include MYCN amplifications driven by extrachromosomal DNA in NB and EWSR1::FLI1 fusions caused by chromoplexy in Ewing sarcoma." (PMID 41228232, 2025). "For fusions, the EWSR1::FLI1 fusions were frequently and only found in bone and soft tissue sarcomas, specifically Ewing sarcomas, as their pathogenic hallmark." (PMID 41312385, 2025). "We conclude that STAG2 loss in Ewing sarcoma leads to transcriptional changes that extend beyond EWS::FLI1 target genes and that most likely contribute to adverse prognosis." (PMID 39487368, 2024). "We next examined changes in gene expression unrelated to EWS::FLI1 in STAG2 deficient Ewing sarcoma cells." (PMID 39487368, 2024). "The 3′ gene partner is important for diagnostic classification as various partners (e.g., FLI1 in Ewing sarcoma, WT1 in desmoplastic small round cell tumor) are characteristic of distinct tumor entities." (PMID 37686670, 2023). "Certain subtypes are strongly associated with genetic fusions, such as Ewing’s sarcoma (EWSR1::FLI1), alveolar rhabdomyosarcoma (PAX3/7::FOXO1), and synovial sarcoma (SS18::SSX1/2/4)." (PMID 36980578, 2023). "Instead, the epigenome of Ewing sarcoma (EWS) cells reflects the regulatory state of genes associated with the DNA binding activity of the fusion oncoproteins EWSR1::FLI1 or EWSR1::ERG." (PMID 38187702, 2023). "MYBL2 has been identified as a direct target of EWSR1::FLI1 with germline polymorphisms associated with activation in Ewing sarcoma and RRM2 overexpression is associated with poor prognosis Ewing sarcoma." (PMID 36793594, 2023). "The fusion protein EWS::FLI1, the causative mutation of Ewing sarcoma, arises from a genomic translocation that fuses the low-complexity domain (LCD) of EWS (EWSLCD) with the DNA binding domain of the ETS transcription factor FLI1." (PMID 37961424, 2023). "EWS/Fli1 is a known inducer of DNA damage, and Ewing Sarcoma cells are relatively deficient in DNA repair." (PMID 30237855, 2018). "FLI1 was identified as a hallmark of Ewing sarcoma by a mechanism of EWS-FLI1 fusion oncoprotein and an oncogenic regulator in malignant phenotype promotion." (PMID 28286742, 2017). "SOX2, a key regulator of pluripotency in ESCs, was initially linked to Ewing’s sarcoma by the observation that MSCs transfected with EWS/FLI1 displayed features of ESFT CSCs." (PMID 26969300, 2016). "FLI-1 acts as an oncogene, and the etiology of a number of virally induced leukemias, as well as human Ewing's sarcoma, has been associated with FLI-1 over-expression." (PMID 27304058, 2016). "The suppression of EWS/FLI1 also leads to a selective decrease in protein expression of the Ewing sarcoma super-enhancer-associated genes CAV1 and CCND1 versus a vinculin control." (PMID 26337082, 2015).
Ewing sarcoma (continued). "Transcription factors were once considered undruggable, but our approach complements other experimental demonstrations for EWS:FLI1 in pediatric Ewing’s sarcoma and MLL-associated pediatric leukemias." (PMID 25030697, 2014). "Abnormal expression of FLI1 is associated with AML and T-cell lymphoma, while FLI1 fusion proteins are linked to Ewing sarcoma and prostate cancer." (PMID 24827933, 2014). "A part of the molecular pathogenesis underlying Ewing's sarcoma is the overexpression of EWS/ETS or EWS/FLI-1 fusion oncogenes that prevent MSC differentiation along the adipogenic and osteogenic lineage." (PMID 21437219, 2011). "Ewing sarcoma carries few mutations other than the pathognomonic EWS/Fli1 gene fusion, and previous studies have demonstrated that while these tumors do not have genomic heterogeneity, there is transcriptional heterogeneity observed in cell lines and xenografts." (PMID 38875295, 2024). "Therefore, in this study, we aimed to investigate the expression of FLI-1 in these tumors, focusing on high-grade lesions, which presents a diagnostic challenge by mimicking Ewing’s sarcoma." (PMID 38280044, 2024). "Consequently, FLI-1 is a diagnostic marker for Ewing’s sarcoma in small blue round cell and vascular origin tumors." (PMID 38280044, 2024). "Finally, recent single cell analyses of Ewing sarcoma PDXs linked EWS::FLI1 activity and metabolic state, revealing that differential transcriptional signatures of glycolysis and hypoxia are positively correlated with the level of fusion activity." (PMID 36505823, 2022). "The overexpression of FLI-1 has been associated with some types of leukemia and Ewing’s sarcoma." (PMID 36555675, 2022). "Supporting this hypothesis, Ewing sarcoma cells only retained the single EWS allele due to the formation of EWS/FLI1, which may result in reduced EWS protein levels." (PMID 25617839, 2015). "A major genetic hallmark of Ewing sarcoma is the aberrant fusion gene EWS/FLI1." (PMID 25617839, 2015). "Second, only a single EWS allele is retained in Ewing sarcoma cells due to the generation of EWS/FLI1 by chromosomal translocation, which may induce haploinsufficiency." (PMID 25617839, 2015). "Thus, an alternative approach to identifying pathogenic miRs, including those driven by EWS/Fli1, in Ewing Sarcoma is comparison of miR expression profiles between Ewing Sarcoma and MSCs." (PMID 23543617, 2013). "We investigated whether an anti-IGF-1R antibody acts via a pathway that could also be suppressed by small interfering (si) RNA against the EWS/FLI-1 fusion protein, the hallmark of Ewing's sarcoma." (PMID 22022506, 2011). "Therefore, EWS::FLI1 is considered a causative oncoprotein for Ewing sarcoma." (PMID 36533189, 2022). "In Ewing sarcoma (EwS), variations in EWS::FLI1 (EF) fusion oncoprotein activity have been associated with epithelial-mesenchymal plasticity (EMP)." (PMID 41484205, 2026). "EWSR1::FLI1 is the only genetic alteration in an otherwise unaltered genome of Ewing sarcoma tumors." (PMID 42295992, 2026). "Background/Objectives: The oncoprotein EWS::FLI1 is a chimeric transcription factor that aberrantly brings transcriptional deregulation relevant to Ewing sarcoma." (PMID 41751220, 2026). "Treatment with the small molecule SP-2509 results in reversal of the transcriptional activity of the FET fusion that causes Ewing sarcoma, EWSR1::FLI1." (PMID 40852926, 2025). "Ewing sarcoma tumouroids preserved characteristic EWSR1 rearrangements with erythroblast transformation-specific (ETS) family of transcription factors such as FLI1, ERG and ETV1." (PMID 41034452, 2025). "IHC revealed intense positivity for Ki-67 (70%), CD99, vimentin, and FLI-1, establishing the diagnosis of extraosseous Ewing's sarcoma." (PMID 40896068, 2025). "It has been shown that subpopulations of Ewing sarcoma cells termed “EWS::FLI1 low” represent an aggressive population of Ewing cells that demonstrate increased TGFβ signaling." (PMID 40858520, 2025).
Ewing sarcoma (continued). "Case presentation: 36-year-old man with rectosigmoid mass showing small round blue cells with pseudorosettes, CD99 and FLI1 positive, diagnosed as Ewing sarcoma; managed with surgical resection followed by chemotherapy." (PMID 41458270, 2025). "A number of Ewing sarcoma cell lines carrying the defining EWSR1::FLI1 fusion have already been established from both tumor and pleural effusion samples." (PMID 40134582, 2025). "Two prominent members of the ETS family in the pathogenesis of specific cancers are FLI1 in Ewing sarcoma (translocation EWS-FLI1) and ERG in prostate cancer." (PMID 41425714, 2025). "A large diversity offusion oncogenes was observed, primarily in one tumor, the three most commonbeing: EWSR1::Fli1 (n = 13) observed in Ewing sarcomas, PAX3::FOXO1 (n = 12) inrhabdomyosarcomas, and ETV6::RUNX1 (n = 8) in childhood leukemias." (PMID 40093400, 2025). "Nuclear expression of FLI-1, a transcription factor from the Ets family that is frequently involved in the pathogenesis of Ewing sarcoma, was also observed." (PMID 41281128, 2025). "This fine-tuning of such biological determinants has been termed the “Goldilocks principle” as related to expression levels of EWSR1::FLI1 in Ewing sarcoma, for example." (PMID 40299558, 2025). "Further, in vivo delivery of an EWSR1::FLI1 disrupting dual intron targeting system led to lower Ki67 proliferative index, higher levels of cleaved caspase-3 and prolonged survival in an Ewing sarcoma mouse model." (PMID 41190236, 2025). "FLI1’s biologic role is altered in Ewing sarcoma (ES), a rare tumor that affects children, adolescents, and young adults." (PMID 41283512, 2025). "In line with previous transcriptomic studies, EWSR1::FLI1-KD cells formed an intermediate population, bridging Ewing sarcoma cell lines and MSCs." (PMID 41444391, 2025). "The most frequent gene fusion identified in Ewing sarcoma is EWSR1::FLI1 fusion, and the second most common fusion is EWSR1::ERG." (PMID 40861426, 2025). "Even ETS-family transcription factors, including ERG and FLI-1, despite exceptional sensitivity, lack specificity due to their expression in prostate adenocarcinoma, Ewing sarcoma, and other malignancies." (PMID 40666093, 2025). "FLI1 is a transcription factor in the ETS family expressed in Ewing sarcoma and angiosarcoma, as well as in an increasing list of neoplasms." (PMID 40909976, 2025). "Neural crest precursors have also been implicated in neuroblastoma, melanoma, and Ewing sarcoma (a family of bone and soft-tissue cancers with EWS::FLI1 or EWS::ERG rearrangements)." (PMID 41155410, 2025). "EWS::FLI1 is an attractive therapeutic target in Ewing sarcoma tumors because it is required for tumorigenesis, but directly targeting this oncoprotein has been challenging despite significant efforts over the past three decades." (PMID 40478628, 2025). "EWSR1-FLI1 rearrangement is the molecular signature described in pancreatic Ewing sarcoma/primitive neuroectodermal tumor, which immunohistochemically translates into FLI1 nuclear staining." (PMID 40668487, 2025). "In this study, upon expression of EWSR1::FLI1 in human pediatric mesenchymal stem cells, considered the putative cell of origin of Ewing sarcoma, we unraveled the genome-wide redistribution of H3K27me3." (PMID 41085408, 2025). "As an example, pan-BET inhibitors have been reported to suppress the transcriptional activity of the EWS::FLI1 transcription factor in both in vitro and in vivo xenograft experiments in Ewing Sarcoma." (PMID 41166819, 2025). "The literature suggests that the Ewing sarcoma–FLI1 fusion oncogene directly regulates the expression of several enzymes involved in de novo serine and glycine biosynthesis and in one-carbon metabolism." (PMID 40698729, 2025). "Ewing sarcoma derived EVs contain the EWSR1::FLI1 transcript and induce pro-inflammatory cytokine release from myeloid cells and direct them towards immunosuppressive phenotypes in vitro." (PMID 40442778, 2025).
Ewing sarcoma (continued). "Historically, the effect of TGFβ signaling in Ewing sarcomas has been assumed to be of limited consequence because of the repression of TGFβR2 by the EWS::FLI1 oncoprotein." (PMID 40858520, 2025). "The differential location and partnership identified for each of the KDM6 demethylases in Ewing sarcoma suggest that KDM6B specifies EWSR1::FLI1 for the most active regions and KDM6A signals for a specific set of enhancers that commit to neural lineage." (PMID 41085408, 2025). "Prior studies demonstrated that EWS::FLI1 is associated with high replication stress states, in which CDK12/13 mediates the transcriptional activity of DNA damage repair in fusion-positive Ewing sarcoma." (PMID 40760094, 2025). "A study in Zebrafish reported that conditional expression of the EWSR1::FLI1 transgene in a trunk neural crest cell may cause transcriptional hijacking and mesoderm lineage reprogramming, which might underlie the formation of neoplasms reminiscent of human Ewing sarcoma." (PMID 40442778, 2025). "Knock down (KD) of EWS::FLI1 in Ewing sarcoma cellular models also causes upregulation of several genes, but the mechanisms of EWS::FLI1-mediated repression are less clear." (PMID 39487368, 2024). "The widespread epigenetic re-programming of Ewing sarcoma cells by EWSR1::FLI1 results in substantial heterogeneity and consistent enhancer hypomethylation." (PMID 38775200, 2024). "Ewing sarcoma is an aggressive bone and soft-tissue cancer that is caused, in the majority of tumors, by an aberrant gene fusion between the EWSR1 and FLI1 genes." (PMID 39201282, 2024). "Along these lines, different HOX family members were found among the most upregulated genes in a BCOR::MAML3 sarcoma when compared to Ewing sarcoma with EWSR1::FLI1 fusions and CIC::DUX4 positive sarcomas." (PMID 38611033, 2024). "The ceRNA networks centered on FLI1 have rarely been reported, and most have been characterized in Ewing sarcoma." (PMID 38448802, 2024). "FLI1 has been targeted as the receptor of Ewing sarcoma for small inhibitory molecules for its DNA‐binding domain." (PMID 39090739, 2024). "While EWS-FLI1 translocation is critical for development of Ewing’s sarcoma, FLI1 overexpression is observed in various human cancers including leukemias, breast cancer, and melanoma." (PMID 39769192, 2024). "To further validate our findings, we confirmed senescence induction by iP300w through β-Gal staining in additional EWS::FLI1-driven Ewing sarcoma cell lines, including CHLA25, A4573, and CHLA9." (PMID 39367409, 2024). "Taken together, these results are in agreement with the formation of cohesin STAG2-dependent contacts in response to the presence of EWS::FLI1 in Ewing sarcoma cells, most prominently at long GGAA repeats." (PMID 39487368, 2024). "Ewing sarcoma tumors are driven by the fusion gene EWS/Fli1, and while these tumors are genetically homogenous, the transcriptional heterogeneity can lead to a variety of cellular processes including metastasis." (PMID 38875295, 2024). "For example, EWSR1‐FLI1 is a fusion protein between EWSR1 RNA‐binding protein and FLI1 TF, leading to the onset of Ewing sarcoma." (PMID 39090739, 2024). "The EWS/Fli1 fusion protein is an aberrant transcription factor that is essential to the oncogenesis of Ewing sarcoma, and multiple studies have led to the identification of over 1,000 genes that are directly or indirectly induced or repressed." (PMID 38875295, 2024). "This promiscuity also occurs in Ewing sarcoma, in which FLI1 can be replaced by ERG (5% of cases) or other ETS TF family members." (PMID 38339014, 2024). "STAG2 loss-of-function mutations promote metastasis in Ewing sarcoma, a pediatric cancer driven by the fusion transcription factor EWS::FLI1." (PMID 39487368, 2024). "This clinical trial aims to determine the maximum tolerated dose and safety of pbi‐shRNATM EWS/FLI1 Type 1 lipoplex in patients with advanced Ewing's sarcoma." (PMID 38919334, 2024).